TNF (tumor necrosis factor)
Diseases named in the same sentence as TNF in open-access papers (continued):
Sharing a sentence is not in itself a finding about the gene and the disease.
cancer (continued). "TNF is elevated in some patients with cancer cachexia, and it was hoped that various agents inhibiting TNF would be effective treatment." (PMID 36358681, 2022). "Overall, we identified TNFα as a potential angiogenic stimulus driving the pre-metastatic niche for homing metastatic cancer cells through VCAM-1 upregulation." (PMID 36290384, 2022). "Chronic IR is found in malignant tumors and presumed to contribute to cancer cachexia due to chronic exposure to proinflammatory cytokines, tumor necrosis factor (TNF)-α, IL-6, and insulin growth factor-binding protein, leading to IR." (PMID 35795140, 2022). "Pomalidomide, a clinically available immunomodulatory imide drug (IMiD) used in cancer therapy, lowers TNF-α generation and thus has potent anti-inflammatory actions." (PMID 35631536, 2022). "This scenario, and the strong evidence on the pro-metastatic roles of TNFα and its receptors in many cancer types, suggest that the pro-cancer and pro-metastatic functions of the TNFα-TNFR network dominate over their protective functions in malignancy." (PMID 35663982, 2022). "The tumor necrosis factor (TNF)/TNF receptor pathway affects the survival of cancer patients, and the potentially functional genetic variations of TNF/TNFR signaling pathway genes affect the survival rate of NSCLC patients." (PMID 35910766, 2022). "This will generate its activation and therefore the production of cytotoxic inflammatory mediators such as cytokines, chemokines, and tumor necrosis factor-alpha (TNF α) which can exert lung adverse effects and even cancer in an indirect manner." (PMID 35808152, 2022). "Based on these results, we examined the effects of a toxin-conjugated secondary antibody in cetuximab- and TNF-α-treated human cancer cells in vitro." (PMID 35798841, 2022). "As a transcription factor, AP-1 is also involved in the production of inflammatory cytokines such as IL-6 and TNFα, which supports the malignant phenotype of cancer cells." (PMID 35964097, 2022). "It is possible that clinical trials based on elevated biomarker levels (such as IL-1β, IL-6, or TNF) in each individual patient will allow a more targeted approach to ameliorating cancer cachexia." (PMID 36358681, 2022). "Persistent M1 polarization in turn can be induced by apoptotic cancer cells, which form a feedback loop to maintain TNFα and nitric oxide production." (PMID 36587223, 2022). "For example, IL2-STAT5 signaling, IL6-STAT3 signaling and TNFα signaling were negatively correlated with m7Gscore among cancers." (PMID 36339001, 2022). "In fact, small molecular inhibitors of TAK1 or IKKβ are capable of inducing RDA in a TNF-dependent manner in some cancer and autoimmune disease models by dysregulating RIPK1 phosphorylation." (PMID 36171264, 2022). "There is now substantial evidence that TNF-α is involved in the promotion and progression of experimental and human cancers." (PMID 35980113, 2022). "Reduced production of the cytotoxic cytokines interferon γ (IFN-γ) and tumor necrosis factor α (TNF-α) favors cancer progression." (PMID 36727049, 2022). "Interferon -γ (IFN-γ) and tumor necrosis factor α (TNFα) can also be secreted to induce cytotoxicity of cancer cells." (PMID 35906622, 2022). "More recently, swimming has been shown to attenuate tumor growth and cancer-related muscle atrophy by downregulating the expression of proinflammatory proteins including NF-κB, p-NF-κB, TNF-α, IL-1β, and IL-6." (PMID 36505042, 2022). "It has been previously shown in cancer that c-MET expression in neutrophils is regulated by TNFα-dependent NF-κB activation." (PMID 35041723, 2022). "Macrophages were the primary cell populations secreting TNF-α, and macrophage-mediated inflammatory responses have been demonstrated to facilitate cancer metastasis." (PMID 36291863, 2022). "The two most frequently cited in vitro IC/BPS models include LPS‐ and TNFα-induced inflammation of cancer RT4 and T24 urothelial cells." (PMID 36045687, 2022).
cancer (continued). "A study demonstrated that cytokine mediators and growth factors (IL-1, IL-4, IL-6, TNF-α, IFN-γ, TGF-β) regulate the control of the central nervous system in cancer patients, despite the continual loss of skeletal muscle induced by a number of processes." (PMID 35159388, 2022). "For example, multiple studies examining the safety profile of anti-TNF agents report higher rates of severe infections, cancer, and death in elderly patients compared to younger patients." (PMID 36844648, 2022). "The importance of IL-1β in cancer invasion was shown in a squamous cell carcinoma model through the capacity of inducing TNF-α expression." (PMID 35681719, 2022). "KEGG and the hub gene-pathway network indicated a few signalling pathways, such as cytokine-cytokine receptor interaction, the IL-17 signalling pathway, TNF signalling pathway, transcriptional misregulation in cancer, and chemokine signalling pathway." (PMID 35937390, 2022). "The cells activated macrophages and lymphocytes, and stimulated production of tumour necrosis factor α (TNFα) that regulates inflammatory responses required to attack malignant neoplasm." (PMID 36144335, 2022). "Pro-tumorigenic cytokines secreted by neutrophils and platelets, including vascular endothelial growth factor, tumor necrosis factor-α, and interleukin-10, can contribute to cancer progression." (PMID 35006344, 2022). "KEGG analysis suggested that DEIRRGs were mainly associated with cytokine-cytokine receptor interaction, TNF signaling pathway, NOD-like receptor signaling pathway, pathways in cancer, and TGF-beta signaling pathway." (PMID 35535346, 2022). "Interferon-γ (IFN-γ), TNF-α, and granulocyte-macrophage colony-stimulating factor (GM-CSF) are some of the cytokines and growth factors secreted by NK cells to kill cancer cells." (PMID 35326729, 2022). "The robust anti-inflammatory and anti-cancer effects of piclidenoson and namodenoson are mediated via their ability to inhibit the production of inflammatory cytokines such as tumor necrosis factor (TNF)-α, interleukin (IL)-12, interferon-ɣ, IL-17, and IL-23." (PMID 35744805, 2022). "APOBEC3B is not only regulated by TNF-α to affect the evolution of cancer cells in the inflammatory microenvironment but also acts as a DNA dehydrogenase to effectively inhibit retroviral replication and retrotransposon migration." (PMID 36419192, 2022). "Anti-TNF therapy are already used for several inflammatory diseases and have been shown effective in some cancers." (PMID 35401557, 2022). "Results of pathway enrichment analysis show lipid and atherosclerotic pathways, IL-17 signaling pathways, AGE-RAGE receptor signaling pathways, TNF signaling pathways, and some cancer signaling pathways." (PMID 36249768, 2022). "A recent review on the topic suggests that short course TNF inhibitors are safe irAE treatment for cancer patients undergoing ICI therapy." (PMID 35844493, 2022). "It was found that the risk factors of the increased prevalence of CRCI were normally involved in social–demographic factors, cancer-therapy-related factors, psychological factors, and some cytokines including IL-6, TNF-α, sTNRFII, etc.." (PMID 35448193, 2022). "ADCK2 depletion suppressed tumor necrosis factor α (TNFα)-induced hypoxia-inducible factor-1 (HIF-1α) stability in cancer cells." (PMID 36439873, 2022). "Heteronemin also inhibits the expression of proinflammatory cytokines, such as IL-1 and TNF-α, which are involved in the pathogenesis of cancer development." (PMID 35705962, 2022). "The KEGG pathway enrichment analysis demonstrated the enrichment of target genes in several key cancer-related signaling pathways, including the cancer pathways, TNF signaling pathway, PI3K-Akt signaling pathway, and HIF-1 signaling pathway." (PMID 35360660, 2022). "This is particularly true for TNF-α antagonists, as this cytokine induces the necrosis of cancer cells in vitro." (PMID 35158989, 2022).
cancer (continued). "The extensive dataset in the Swedish cancer registers was used again in 2018 with a larger patient cohort to analyze TNF biologicals in cancer recurrences." (PMID 36358688, 2022). "TNF-α is produced by various cancers in small quantities and can promote cancer progression in various ways which are still under investigation." (PMID 34480199, 2022). "The cell-free synthesized human TNF-α demonstrated a cytotoxic effect in a concentration-dependent manner on test cancer cells." (PMID 35205024, 2022). "The dual inhibition sustained an increased production of IFNγ, TNFα, IL-12 and IL-6 by PBMCs, that contribute to expression of Ido-1 on cancer cells." (PMID 36419183, 2022). "All 7 ingredients were involved in infections and cancers and inflammatory responses such as IL-17, TNF, and HIF-1 signaling pathways, which was corroborated by our in vivo experiments." (PMID 36091591, 2022). "The biggest impediment to using TNF-α as an anti-cancer agent is its systemic toxicity and strategies that limit its systemic distribution through local administration in patients have been investigated." (PMID 35433433, 2022). "First, cancer cells and TAMs produce TNFα and IL1-β, which activate CAFs to produce thymic stromal lymphopoietin (TSLP)." (PMID 35205732, 2022). "This killing TNFR1 signaling pathway makes sTNF-α protein (mature TNF-α) a promising drug for cancer treatment in clinical trials and market." (PMID 35205024, 2022). "Some of the important pathways were- pathway in cancer, IL-17 signaling, TNF signaling, AGE-RAGE signaling in diabetic complications, and several other infectious disease related pathways." (PMID 36591238, 2022). "In fact, the presence of TNF-α-secreting macrophages can push cancer cells to take on a more aggressive basal-like subtype." (PMID 36077755, 2022). "The anticancer activity of purified human TNF-α was assessed against three human cancer cell lines: Caco-2, HepG-2 and MCF-7." (PMID 35205024, 2022). "MyD88 inhibitor, 4210, also slightly reduced TNFα levels in the culture medium treated with LPS, suggesting that LPS stimulates TNFα production by the cancer cells through a MyD88-dependent pathway." (PMID 36119107, 2022). "The CCNGG-based DMGs were involved in transcriptional misregulation in cancers, TNF signaling pathway, apoptosis, focal adhesion, NF-kB signaling pathway and Oxidative phosphorylation." (PMID 35544480, 2022). "WEE1 overexpression abrogates immune cell killing, for example by protecting cancer cells from granzyme B/TNFα induced cell death." (PMID 36276148, 2022). "As a proinflammatory factor, the tumor necrosis factor is closely related to the occurrence of cancer." (PMID 35784334, 2022). "Cancer-induced inflammation inhibits hematopoiesis by the interaction of interleukin 6 and tumor necrosis factor-alpha (TNF-α)." (PMID 36364711, 2022). "To determine the effect of TNF-α on macrophage-mediated CXCL1 production in cancer cells, we treated B16F10 cells with the CM of mock-transfected or KLK6-transfected RAW 264.7 cells in the presence or absence of the TNF-α neutralizing antibody." (PMID 36552865, 2022). "We also observed an increase in TNF signals from monocytes to TReg cells in lung tissue of advanced cancer versus healthy lung." (PMID 35493454, 2022). "As with TNF-α, tryptase is uniquely pre-stored in MC granules, released upon IgE-FcεRI crosslinking and enters the cancer cells following their IgE-mediated interaction with MCs." (PMID 35740607, 2022). "TNF-α induces Nur77 expression by activating JNK, which leads to attenuating the death effect of TNF-α in cancer cells." (PMID 35370650, 2022). "FGF2 causes a significant reduction of IFN-γ, TNF-α and granzyme B production by in vitro stimulated CD8 T cells and decreased their efficiency in killing target cancer cells." (PMID 35479076, 2022).
cancer (continued). "It is therefore likely that localized cancer arising within the native prostate tissue benefits from sustained local inflammatory networks driven by IL-6, TNFα and SELE." (PMID 36371231, 2022). "IL‐17 cytokines family can activate the production of NF‐κB, IL8, IL6, TNF‐α, and IL1b, contributing to various inflammatory diseases and cancers." (PMID 35373393, 2022). "For these reasons, TNF promotes metastasis in cancer cells and invasive abilities of resident cells of the joint during rheumatoid arthritis." (PMID 35401557, 2022). "Conversely, TNF induces cancer cell death and has been proposed as a potential cancer therapeutic agent." (PMID 36230879, 2022). "Early attempts to treat cancer using the TNF and Fas ligand (FasL) as DR agonists showed disappointing results due to lack of efficacy or prohibitive preclinical toxicity." (PMID 36496977, 2022). "Another antitumor property of QC is its ability to inhibit inflammatory mediators including IFN-γ, IL-6, COX-2, IL-8, iNOS, TNF-α, and many other cancer inflammatory mechanisms." (PMID 36233051, 2022). "MDSCs are crucial components of TME that facilitate cancer growth by secreting immunosuppressive cytokines such as TNF and TGFβ, inadvertently allowing cancer cells to evade the patient’s immune system." (PMID 35563674, 2022). "Compared with factors of IL6, TNFα seems to be less determinate in predicting the outcomes of cancer survival." (PMID 35859928, 2022). "The mouse models containing MCF-7 cell lines together with a cytotoxin-induced TNF-α cassette exhibited a stronger cancer reduction response to DOX-based treatments compared with mouse models containing MCF-7 cell lines overexpressing TNF-α." (PMID 35814435, 2022). "The newly diagnosed cancer incidence rate per 1000 person-years in the TNF inhibitor and nbDMARD cohorts was 6.5 and 15.0, respectively, before matching and 6.5 and 15.6 after matching." (PMID 35945635, 2022). "The function of TNF in immune cells is generally well established, and studies related to cancer malignancy have also been reported." (PMID 36613819, 2022). "The interplay between inflammation and cancer implicates inflammatory mediators such as NF-κB, TNF, inducible nitric oxide synthase (iNOS), cyclooxygenases (COX), and lipoxygenases (LOX)." (PMID 36142391, 2022). "In human cancer cell lines, PANoptosis can be activated by TNF-α and IFN-γ co-treatment to kill the cancer cells." (PMID 36329783, 2022). "Acute destruction of FAP+ (fibroblast-expressing activation protein) CAFs caused rapid hypoxic necrosis of cancer and stromal cells that is interferon-γ (IFN-γ)- and tumor necrosis factor-α (TNF-α)-dependent." (PMID 36077755, 2022). "Yet, to date, only a very limited number of clinical studies had analyzed the therapeutic value of TNFα-TNFR antagonists in cancer treatment." (PMID 35663982, 2022). "According to numerous findings, TNF-α is elevated in various cancers, with higher levels in preneoplastic and neoplastic tissues, similarly to the way TNF-α-induced inflammation is exhibited by IL-1β, a pro-inflammatory cytokine." (PMID 36294905, 2022). "Based on the conducted research, it was found that an increase in the amount of the p21 protein protected cancer cells from apoptosis induced by TNF-α." (PMID 35563410, 2022). "The results obtained demonstrated that the mAb-EGFR complex was markedly and synchronously internalized via the p38-mediated phosphorylation of EGFR upon a stimulation with TNF-α and cytotoxic anti-cancer agents." (PMID 35798841, 2022). "TNF was discovered as the first immune molecule to have robust activity to kill cancer cells in 1975." (PMID 35795050, 2022).
cancer (continued). "Meanwhile, KEGG enrichment further elucidated possible pathways such as proteoglycans in cancer, cAMP signaling pathway, and TNF signaling pathway." (PMID 35495130, 2022). "Previous reports showed that PD-L1 can be induced in MDS cells by IFNγ and TNFα, although a variety of other factors (i.e., IL-10, FasL, and IL-17A) have been shown to upregulate PD-L1 in other cancer types." (PMID 35992887, 2022). "Tumor Necrosis Factor was found in 1975 and its main activity was assumed to be lethal for cancer cells and to be able to kill tumors, hence the name." (PMID 36358688, 2022). "Although several publications have indicated an association between fatigue and systemic cytokines such as IL-1β, IL-2, IL-6, IP-10, and TNF in cancer patients, the results are conflicting." (PMID 36350483, 2022). "The most common cancer experienced among tofacitinib users was lung cancer, while breast cancer was most common among patients receiving the TNFα inhibitor." (PMID 36110853, 2022). "TNF-α upregulated the expression of CXCL1/2 in cancer cells through the NF-κB signaling pathway, thereby amplifying the CXCL1/2-S100A8/9 loop and causing chemoresistance." (PMID 34813418, 2022). "Receptor–ligand pairs that mediate cellular communication between cancer cells and other cells are significantly enriched in the pathways of leukocyte migration, tumor necrosis factor response, and cell chemotaxis." (PMID 36077333, 2022). "Systemic inflammation too plays a role in the progression of cancer cachexia: proinflammatory cytokines, such as IL-6 or TNF-α, are elevated in some cachectic patients’ plasma and cancer-bearing models." (PMID 35406586, 2022). "The apoptosis caused by LPS plus SM-164 is blocked by toll-like receptor 4 (TLR4) or MyD88 inhibitor, which inhibits LPS-induced TNFα production by the cancer cells." (PMID 36119107, 2022). "The cytotoxic activity and anti-inflammatory activity through inhibition of TNF-α production is a means of evaluating cancer prevention and therapy." (PMID 35953870, 2022). "Cancer cells produce pro-inflammatory cytokines such as IL-6 and TNF-α, which produce inflammatory reactions between cancer cells and their hosts." (PMID 35057531, 2022). "NFκB signal is implicated in this TNFR1 mediated hepatocyte death as deletion of IKKβ or NEMO, two NFκB signal modulators resulted in spontaneous progression of TNFα mediated hepatitis to cancer." (PMID 36276076, 2022). "The connections of TNFα, IL-1β and IFNγ with the PD-L1/PD-1 axis, as well as with cancer-related inflammation, have led us to characterize the impact of these cytokines—each alone and in different combinations—on the expression of PD-L1 by TNBC cells." (PMID 35884574, 2022). "One nonrandomized phase II trial was conducted to observe the effects of celecoxib (COX-2 inhibitor) on patients with cancer cachexia and reported a significant improvement in body weight and quality of life and a decrease in TNF alpha." (PMID 35326441, 2022). "Previous studies have shown that TNF super family members are induced after CAP treatment in cancer cells." (PMID 35260587, 2022). "Another important consideration is that cytokines, such as interleukin-1, interleukin-6, and tumor necrosis factor-α, inhibit the synthesis of albumin, and the levels of these cytokines are increased in patients with malignant tumors." (PMID 36316884, 2022). "One study found that cancer cells develop resistance to granzyme B/TNFα-mediated cytotoxic T cell killing by activating the G2/M cell cycle checkpoint." (PMID 36276148, 2022). "For instance, mitochondrial ROS activate MAPK/ERK activity, which contributes to the secretion of TNF-α and subsequently promotes cancer invasion." (PMID 35740025, 2022).